CIP2A (cellular inhibitor of PP2A)
Diseases named in the same sentence as CIP2A in open-access papers (continued):
Sharing a sentence is not in itself a finding about the gene and the disease.
liver cancer (8 papers, 2014 to 2025). An epithelial or non-epithelial malignant neoplasm that arises from the liver. "Initially identified as a tumor-associated antigen (TAA) in gastric and liver cancer patients, CIP2A was overexpressed in a variety of cancer types." (PMID 25109354, 2014). "CIP2A was initially identified as a tumor-associated autoantigen in gastric and liver cancer." (PMID 25109354, 2014). "Cancerous inhibitor of PP2A (CIP2A) was originally identified as a tumor-associated autoantigen in gastric and liver cancer." (PMID 25109354, 2014). "In BC, CIP2A-BP functions mainly by competing with PP2A for CIP2A, while in liver cancer, there may be unknown targets that interact with CIP2A-BP, resulting in opposite functions." (PMID 41291707, 2025). "JXE-23, a pimarane-type diterpene, exhibits potent anti-cancer effects in HepG2 liver cancer cells by inducing G2/M cell cycle arrest and protective autophagy, and modulating the CIP2A/p-AKT/c-Myc signaling pathway, suggesting its potential as a lead compound in anti-cancer drug development." (PMID 39315094, 2024). "Initially, CIP2A was identified as an oncogene in gastric and liver cancer." (PMID 29464081, 2018). "For instance, in liver cancer, CIP2A overexpression increased AKT phosphorylation." (PMID 25663244, 2015). "CIP2A is a human oncoprotein that was initially identified in patients with gastric and liver cancers, which has unknown function due to the lack of the homology to any known proteins." (PMID 27144172, 2016).
oral cancer (8 papers, 2013 to 2023). "This formulation exhibited efficient therapeutic silencing of the CIP2A (Cellular Inhibitor of PP2A) oncogene in human tongue squamous cell carcinoma and reduced the invasiveness and anchorage-independent growth of oral cancer cells." (PMID 34575464, 2021). "Repression of CIP2A coding sequence was reported as the mechanism by which tumor suppressor miR-375 regulated MYC expression in oral cancers." (PMID 25015035, 2014). "CIP2A expression and localization in oral carcinoma and dysplasia has been reported in different studies." (PMID 25015035, 2014). "CIP2A has been targeted using fusogenic-oligoarginine peptide-mediated delivery of siRNAs in oral cancer cells." (PMID 25015035, 2014). "In an effort to further characterize 599 peptide-mediated silencing of CIP2A in oral cancer cells the duration of gene silencing, dose-dependent gene silencing, and activity of silencing in serum were also assessed." (PMID 24019920, 2013). "Quantitation by real-time PCR demonstrated a significant knockdown in CIP2A mRNA levels in both oral cancer cell lines treated with the 599/siCIP2A complex compared to control 599/siNT treated cells." (PMID 24019920, 2013). "Most importantly, the 599 peptide-mediated siRNA delivery promoted significant CIP2A mRNA and protein silencing which resulted in decreased oral cancer cell invasiveness and anchorage-independent growth." (PMID 24019920, 2013). "In our previous study, we identified CIP2A as a target of miR-375 in oral cancer." (PMID 24708873, 2014). "Moreover, the ability of the 599 peptide to mediate silencing of the CIP2A oncogene resulting in decreased oral cancer cell invasiveness and anchorage-independent growth demonstrate the therapeutic relevance of this delivery vehicle." (PMID 24019920, 2013). "Thus, to further demonstrate the potential usefulness of the 599 peptide in siRNA-based therapeutics for oral cancer, we tested whether 599 peptide-mediated silencing of CIP2A could affect the invasiveness and anchorage-independent growth properties of oral cancer cells." (PMID 24019920, 2013). "More specifically, a ∼60% and ∼85% reduction in CIP2A mRNA levels was observed in CAL 27 and SCC-25 oral cancer cell lines, respectively." (PMID 24019920, 2013).
melanoma (7 papers, 2014 to 2025). A malignant, usually aggressive tumor composed of atypical, neoplastic melanocytes. "Next, we adopted a loss‐of‐function strategy to knockdown CIP2A expression in melanoma cells to understand its role in role in melanoma progression and in PF's anti‐melanoma activity." (PMID 39399646, 2024). "CIP2A is overexpressed in various tumor types, and we demonstrated that it is also highly expressed in melanoma and is closely associated with metastasis and poor prognosis, highlighting the possibility of developing anticancer drugs by targeting CIP2A." (PMID 39399646, 2024). "To further elucidate the role of CIP2A we transiently downregulated the protein in four melanoma cell lines harboring the common genetic mutations BRAFV600E (WM983b), BRAFV600E/PTENnull (WM9), NRASQ61K (1366) and the less frequently seen HRAS mutation (FEMX1)." (PMID 25663244, 2015). "CIP2A is highly expressed in melanoma and its metastases, and is linked to poor prognosis." (PMID 39399646, 2024). "Additionally, the high expression of CIP2A is associated with melanoma metastasis and poor prognosis, suggesting that CIP2A inhibitors or degraders could become novel antitumor drugs." (PMID 39399646, 2024). "For P1, clusters enriched in ER lumen-associated proteins (CIP2A, OSMR, WWTR1), inflammasome-related proteins, and melanoma-specific proteins (CCND1, MITF, MLANA, NOTCH1) were notable." (PMID 40669378, 2025). "Obviously, PF significantly shortened the half‐life of CIP2A protein in melanoma cells, affecting its stability." (PMID 39399646, 2024). "We confirmed that CIP2A is the direct binding protein of PF and elucidated the mechanism by which PF reduces CIP2A levels in melanoma." (PMID 39399646, 2024). "This study identifies penfluridol (PF) as a promising candidate for treating melanoma, particularly its brain metastases, by targeting and degrading CIP2A via the ubiquitin‒proteasome pathway." (PMID 39399646, 2024). "In this study, through a drug repositioning strategy and screening of various antipsychotics capable of penetrating the BBB, we identified PF as a potential drug of treating melanoma growth and metastasis, including brain metastases, by targeting CIP2A." (PMID 39399646, 2024). "In summary, these data indicate that PF probably promotes CIP2A degradation in melanoma through the UPS pathway." (PMID 39399646, 2024). "Overall, this study not only suggests PF's potential in treating melanoma and its brain metastases but also highlights CIP2A degradation as a therapeutic strategy for melanoma." (PMID 39399646, 2024). "Considering the central role of polyubiquitination in protein degradation, we co‐transfected B16 and A375 cells with plasmids expressing ubiquitin (HA‐Ub) and CIP2A (Flag‐CIP2A) in melanoma cells." (PMID 39399646, 2024). "Compared to normal nevi tissues, CIP2A is upregulated in melanoma and more prominent in metastatic melanoma." (PMID 39399646, 2024). "First, we analyzed the expression levels of CIP2A in normal nevus samples and melanoma in The Cancer Genome Atlas (TCGA) and found that its mRNA was upregulated in melanoma." (PMID 39399646, 2024). "Reducing the expression of CIP2A has demonstrated the ability to decrease cell proliferation, invasion, and migration, while increasing apoptosis in melanoma." (PMID 39399646, 2024). "This study provides preliminary experimental evidence for the potential application of PF in treating melanoma and its brain metastases and offers insights for developing new anti‐melanoma drugs based on CIP2A‐targeted degradation." (PMID 39399646, 2024). "CIP2A overexpression in melanoma correlates with poor prognosis, underscoring its potential as a therapeutic target for the disease." (PMID 39399646, 2024). "PF restores Protein Phosphatase 2A activity, inhibits key oncogenic pathways, and enhances the interaction between E3 ligase von Hippel‒Lindau and CIP2A, leading to reduced melanoma growth and metastasis in animal models." (PMID 39399646, 2024).
melanoma (continued). "In conclusion, our study provides compelling evidence that PF can be repositioned as an effective therapeutic agent for melanoma and its brain metastasis by promoting CIP2A degradation and restoring PP2A activity." (PMID 39399646, 2024). "Restoration of CIP2A levels significantly increased the proliferation of melanoma cells and rescued the inhibitory activity of PF on the growth of these cells." (PMID 39399646, 2024). "This provides a basis for developing novel anticancer drugs targeting CIP2A degradation, thereby opening promising avenues for treating melanoma and its metastases." (PMID 39399646, 2024). "The upregulation of miR-218 inhibits the expression of CIP2A/p90 and meanwhile suppresses the functions of melanoma cells, such as migration, proliferation, invasion, and cell cycle." (PMID 36911405, 2023). "CIP2A expression was analyzed by immunohistochemistry in 17 nevi, 132 primary melanomas and 49 metastases." (PMID 25663244, 2015). "We found CIP2A to be highly expressed in both nevi and melanomas, showing both cytoplasmic and nuclear staining." (PMID 25663244, 2015). "Immuno-blot analysis revealed that melanoma cell lines had an increased level of CIP2A protein compared to cultured melanocytes." (PMID 25663244, 2015). "CIP2A expression, in addition to previously identified melanoma prognostic factors including tumor depth, ulceration, Cyclin A and Ki67 expression, were analyzed using univariate and multivariate Cox regression analysis." (PMID 25663244, 2015). "In superficial spreading melanomas (SSM), high nuclear CIP2A expression was associated with poor overall survival (OS) (P = 0.0018)." (PMID 25663244, 2015). "In this study we have examined expression, clinical relevance and function of CIP2A in melanoma tissues, primary melanocyte cultures and established cell lines." (PMID 25663244, 2015). "Additionally, von Hippel‒Lindau (VHL) is the endogenous E3 ligase for CIP2A, and PF enhances the interaction between VHL and CIP2A, promoting the ubiquitin‒proteasome degradation of CIP2A, thereby inhibiting melanoma growth and metastasis." (PMID 39399646, 2024). "In summary, these data suggest that PF may restore the anticancer activity of PP2A by inhibiting CIP2A, thereby suppressing multiple oncogenic signaling pathways and inhibiting melanoma growth and metastasis." (PMID 39399646, 2024). "Knockdown of VHL in melanoma cells led to increased CIP2A protein expression, suggesting that VHL may be the natural E3 ligase for CIP2A and that PF might enhance the interaction between VHL and CIP2A, thereby increasing CIP2A instability and degradation." (PMID 39399646, 2024). "We reported here that VHL is the E3 ligase for CIP2A in melanoma." (PMID 39399646, 2024). "Furthermore, PF treatment obviously induced CIP2A polyubiquitination in melanoma cells stably expressing Flag‐CIP2A." (PMID 39399646, 2024). "Similarly, Transwell assays showed that reduced CIP2A levels diminished the sensitivity of cells to PF treatment, indicating that PF exerts its anti‐melanoma role in a CIP2A‐dependant manner." (PMID 39399646, 2024). "However, we have also observed a weak nuclear expression of CIP2A in normal cultured melanocytes, which further suggests that CIP2A has a context-dependent role in melanoma progression." (PMID 25663244, 2015). "However, to best of our knowledge, only one previous study has reported on primarily cytoplasmic CIP2A expression in melanomas, which was higher in tumor samples compared to nevi and correlated with poor OS and Breslow thickness." (PMID 25663244, 2015). "For this reason, it is possible that CIP2A might regulate mTORC1 and autophagy in melanoma, which indirectly might affect apoptosis." (PMID 25663244, 2015). "Using established melanoma cell lines, we have examined whether CIP2A is involved in regulation of major proliferation and survival signaling pathways." (PMID 25663244, 2015). "Moreover, knockdown of CIP2A markedly decreased melanoma cells' sensitivity to PF." (PMID 39399646, 2024).
melanoma (continued). "We hypothesized that PF might inhibit melanoma by regulating CIP2A." (PMID 39399646, 2024). "Together these results suggest that AKT might be a CIP2A target in melanoma." (PMID 25663244, 2015). "Next we assessed the levels of CIP2A mRNA and protein in a panel of normal human melanocytes (NHM) and established melanoma lines." (PMID 25663244, 2015). "As seen in other cancer types, CIP2A can influence cMYC and AKT, but our data also suggest that in melanoma it has additional targets which need to be identified." (PMID 25663244, 2015). "In contrast to these results, we found that nuclear CIP2A expression is a marker of reduced OS in SSM whereas this is not the case for NM, suggesting that CIP2A has distinct functions in different melanoma subtypes." (PMID 25663244, 2015). "The role and mechanisms of CIP2A in the development and metastasis of melanoma, as well as its involvement in the mechanisms by which PF inhibits melanoma metastasis, were not clearly articulated in this study." (PMID 39399646, 2024). "Our in vitro results show that CIP2A downregulation slightly reduced the pAKT levels in all melanoma cell lines regardless of their genetic background whereas regulation of cMYC was less profound." (PMID 25663244, 2015). "Inhibitory effects of CIP2A downregulation on proliferation of melanoma cells were not related to the genetic background of the cells." (PMID 25663244, 2015). "Their studies show that miR-218 plays a pivotal role in the development of the disease and by targeting CIP2A and BMI1, miR-218 regulates the proliferation, migration and invasion of the melanoma cell lines A375 and SK-MEL-2, explaining miR-218's pivotal role in melanoma development." (PMID 25015035, 2014). "Furthermore, the majority of benign nevi are senescent lesions that do not progress to melanoma and hence CIP2A might have a different role in this setting." (PMID 25663244, 2015). "The data showed that in melanoma cells with stable knockdown of BRCA1, CUL3, RNF4, UBR5, and CHIP, the reduction in CIP2A levels upon PF treatment was not reversed." (PMID 39399646, 2024). "However, in contrast to CIP2A knockdown, LY294002 treatment did not induce cleavage of Caspase 3, suggesting that CIP2A might regulate apoptosis independently of PI3K/AKT pathway in melanoma cells." (PMID 25663244, 2015).
multiple myeloma (7 papers, 2016 to 2025). "The serine/threonine kinase TGFβ-activated kinase-1 (TAK1) is regulated by CIP2A in a PP2A-dependent manner in multiple myeloma cells." (PMID 41155727, 2025). "An increase in CIP2A expression has been observed in numerous solid tumors and hematologic malignancies, including multiple myeloma (MM)." (PMID 37048102, 2023). "Previous study found that knocking down CIP2A expression inhibited cell proliferation of human multiple myeloma cells and induced early apoptosis via inactivation of PI3K/AKT/mTOR signaling." (PMID 33948919, 2021). "The present study investigated the role of CIP2A in cell proliferation and apoptosis in the human multiple myeloma cell lines RPMI-8226 and NCI-H929 and its potential regulation of PI3K/AKT/mTOR signaling." (PMID 27144172, 2016). "In conclusion, the results of our study indicate that CIP2A acts as an oncoprotein in human multiple myeloma." (PMID 27144172, 2016). "Taken together, the results indicate that CIP2A knockdown modulates multiple myeloma cell proliferation and apoptosis via inhibition of PI3K/AKT/mTOR signaling." (PMID 27144172, 2016). "The role of CIP2A in human multiple myeloma was investigated by knocking down CIP2A expression in RPMI-8226 and NCI-H929 cells and evaluating the effect on cell proliferation." (PMID 27144172, 2016). "The present study investigated the role of CIP2A in human multiple myeloma using the RPMI-8226 and NCI-H929 cell lines." (PMID 27144172, 2016). "Therefore, CIP2A can serve as a potential target for therapeutic agents developed for the treatment of multiple myeloma." (PMID 27144172, 2016). "To clarify the role of PI3K/AKT/mTOR signaling in the regulation of multiple myeloma cell proliferation and apoptosis by CIP2A, we evaluated the effect of IGF-1 which could activate PI3K on RPMI-8226 and NCI-H929 cells." (PMID 27144172, 2016). "Based on these previous results, we predicted that CIP2A might serve as a potential target for therapeutic agents developed for the treatment of multiple myeloma." (PMID 27144172, 2016). "However, the expression and the role played by CIP2A in the pathogenesis of multiple myeloma (MM) remain unclear." (PMID 29263916, 2017). "While compounds such as bortezomib (FDA-approved for multiple myeloma) and Fingolimod (FDA-approved for multiple sclerosis) have shown potential to modulate PP2A or CIP2A activity in preclinical studies, their use specifically for targeting CIP2A in cancer remains experimental." (PMID 41155727, 2025). "The precise function of CIP2A in human multiple myeloma has never been reported." (PMID 27144172, 2016).
acute myeloid leukemia (6 papers, 2011 to 2019). Acute myeloid leukemia (AML) is a group of neoplasms arising from precursor cells committed to the myeloid cell-line differentiation. "CIP2A is over-expressed in acute myeloid leukaemia and associated with HL60 cells proliferation and differentiation." (PMID 25015035, 2014). "CIP2A is also overexpressed in acute myeloid leukaemia and associated with HL60 cells proliferation and differentiation." (PMID 25015035, 2014). "CIP2A overexpression has been found in over 70% of acute myeloid leukemia (AML), ovarian, prostate, lung, colon and gastric cancers, as well as squamous cell carcinomas of the head and neck (HNSCC)." (PMID 25334061, 2014). "Our own bioinformatics analysis of overexpression of CIP2A and components of EGFR-MEK1/2-ETS1 pathway revealed M6 subtype of acute myeloid leukemia (AML) as a cancer type in which CIP2A and representative genes of each level of the pathway are significantly up regulated." (PMID 21445343, 2011).
Alzheimer disease (6 papers, 2018 to 2024). A progressive, neurodegenerative disease characterized by loss of function and death of nerve cells in several areas of the brain leading to loss of cognitive function such as memory and language. "The overexpression of endogenous protein inhibitors of PP2A, SET and CIP2A, is tightly linked to the progression of various human cancers, as well as Alzheimer’s disease." (PMID 30341686, 2018). "As CIP2A is also strongly implicated in Alzheimer ́s disease via regulation of both Tau and APP32,58, these results may have broad relevance to human diseases also beyond cancer." (PMID 36854761, 2023). "In 3XTg Alzheimer’s disease mice model, PPI reduces cognitive impairments and Alzheimer’s disease like pathology via suppressing CIP2A expression and PP2A re-activation." (PMID 38745316, 2024). "In conclusion, our study uncovers a mechanism by which DNA damage-induced Chk1 activation promotes CIP2A-mediated tau and APP hyperphosphorylation and cognitive dysfunction in Alzheimer’s disease and highlights the therapeutic potential of Chk1 inhibitors in AD." (PMID 35286657, 2022).